POLR3A (RNA polymerase III subunit A)
Diseases named in the same sentence as POLR3A in open-access papers (continued):
Sharing a sentence is not in itself a finding about the gene and the disease.
Leukoencephalopathy (2 papers, 2022 to 2024). This term describes abnormality of the white matter of the cerebrum resulting from damage to the myelin sheaths of nerve cells. "Analysis of the leukoencephalopathy panel data of four patients revealed the same homozygous missense variant NM_007055.4: c.2011T>C; p.(Trp671Arg) in exon 15 of POLR3A (10q22.3) that has previously been reported as likely pathogenic according to ACMG/AMP Criteria (PS3, PM2, PM3, PP2, and PP3)." (PMID 39436788, 2024).
myopia (2 papers, 2022 to 2024). "The frequency of myopia in our cohort was lower than that in previously reported patients with POLR3A or POLR3B variants (87%) (P < 0.001)." (PMID 38550343, 2024). "The frequency of myopia in our cohort was lower than that in previously reported patients with POLR3A or POLR3B variants." (PMID 38550343, 2024).
optic atrophy (2 papers, 2018 to 2024). A disorder characterized by loss of optic nerve fibers. "We detected two families with the same mutation in POLR3A; in one patient this was found to be associated with pure HSP, and in another with HSP plus optic atrophy and sensory ataxia." (PMID 30564185, 2018).
progeria (2 papers, 2021 to 2023). "We also focused on the pathogenic genes of other diseases related to progeria, such as POLR3A and POLR3GL, and we only found a heterozygous POLR3A variant, c.1771-6C > A, which is an intron variant, in the WES data." (PMID 34289880, 2021).
viral infection (2 papers, 2023 to 2025). "Three cases with severe viral infection predisposition were associated with POLR3A, IFIH1, and TLR7XL variations." (PMID 41209815, 2025). "Severe viral infection predisposition was seen in 3 patients (POLR3A, IFIH1, TLR7XL) and bacterial susceptibility in 3 others (IRF4, IFNGR1, NCSTN)." (PMID 41209815, 2025).
Action tremor (1 paper, 2025). A tremor present when the limbs are active, either when outstretched in a certain position or throughout a voluntary movement. "We present the case of a woman with a drug-refractory action tremor due to rare compound heterozygous POLR3A mutations." (PMID 40248113, 2025).
ataxia telangiectasia (1 paper, 2022). Ataxia-telangiectasia is the association of severe combined immunodeficiency (affecting mainly the humoral immune response) with progressive cerebellar ataxia. "For some diseases, cryptic splicing variants are in fact very common such as POLR3A variants for recessive spastic ataxia, ATM variants for Ataxia telangiectasia, ABCA4 for Stargardt diseases, and NF1 variants for neurofibromatosis." (PMID 34591693, 2022).
atherosclerosis (1 paper, 2020). A disease characterized by the build-up of fatty material and calcium deposition in the arterial wall resulting in partial or complete occlusion of the arterial lumen. "Currently, no study was carried out to research the function of POLR3A in CAD or atherosclerosis." (PMID 33033488, 2020).
bladder cancer (1 paper, 2021). "In bladder cancer, RNA polymerase III (POLR3A) promotes the proliferation of bladder cancer cells by inhibiting their differentiation; in colorectal cancer, POLR3A is expressed at high levels and is associated with advanced tumor depth, lymph node metastasis, distant metastasis, and poor prognosis." (PMID 34398900, 2021).
extrapyramidal movement disorders (1 paper, 2020). "Recognition of the characteristic MRI pattern, including awareness of the potentially relatively mild T2-hyperintensity and atrophy of the striatum, should trigger genetic testing for POLR3A in patients with unexplained extrapyramidal movement disorders." (PMID 31940116, 2020).
Failure to thrive (1 paper, 2024). Failure to thrive (FTT) refers to a child whose physical growth is substantially below the norm. "Thus, the loss of body weight in Polr3a-tamKI mice demonstrates a more severe failure to thrive phenotype, in line with the widespread expression of the Polr3a mutation." (PMID 39499645, 2024).
primary immunodeficiencies (1 paper, 2021). "However, no errors in innate immune genes or other rare primary immunodeficiencies were discovered; specifically, there were no errors in RNA polymerase III genes (POLR3A and POLR3C)." (PMID 34835092, 2021).
proteopathies (1 paper, 2021). "Alternatively, it is thought that mutations of RNA polymerase III subunit A (POLR3A) or RNA polymerase III subunit B (POLR3B) may induce aggregation of POLR3A and POLR3B proteins, leading to proteopathies (also called proteinopathies) associated with gain of function in POLR3A or POLR3B mutants." (PMID 33535532, 2021).
cancer (17 papers, 2014 to 2025). A tumor composed of atypical neoplastic, often pleomorphic cells that invade other tissues. "This suggests that either multiple mechanisms underlie the targeting of POLR3A by the immune system in SSc, and/or that cancer underlies many cases of SSc, but that in most cases the immune response is capable of controlling the cancer." (PMID 35040440, 2022). "Moreover, ex vivo data show that somatic POLR3A mutations in cancer patients trigger an autoimmune response." (PMID 33506656, 2021). "A recent study reported three independent mutations in human RPC1 (POLR3A) associated with spontaneous cancers that were associated with autoantibodies to RNAP III; The human rpc1-E1072Q occurred at the same invariant residue found in ten of our C1 mutants, E1085G/A/D." (PMID 27518095, 2016). "The observation that these somatic mutations are only found in a minority of cells in the tumor, combined with LOH at the POLR3A locus, strongly suggest that this subgroup of SSc represents natural cancer immunoediting." (PMID 35040440, 2022). "RNA polymerase III subunit A (POLR3A) is involved with autoimmune disease scleroderma, which is a risk factor for cancer." (PMID 28450890, 2017). "In anti-POLR3–positive SSc patients, somatic mutations and loss of heterozygosity (LOH) at the POLR3A locus in the associated cancers were frequent; such genetic changes were not seen in cancers from patients with other immune responses in SSc." (PMID 35040440, 2022). "Indeed, only approximately 20% of anti-POLR3A–positive patients have a cancer identified around the time of SSc." (PMID 35040440, 2022). "The anti-POLR3A–positive/anti-CCAR1–positive patient had no detected cancer, and it is noteworthy that levels of anti-CCAR1 antibodies were very low in this serum." (PMID 35040440, 2022). "POLR3A is a RNA polymerase III subunit and is known as an unfavorable marker in cancer." (PMID 32762727, 2020). "Indeed, the POLR3A locus, coding for the antigenic target of ARA, was altered in cancer tissue specimens from SSc patients carrying ARA, leading to the synthesis of an immunogenic enzyme resulting in T-cell-driven ARA production and SSc onset." (PMID 30157947, 2018). "In a recent study focused on SSc patients with autoantibodies against POLR3A in whom cancer does not emerge, we found that patients who also had autoantibodies against the large subunit of RNA polymerase I (RPA194) had a much lower incidence of cancer than those with antibodies against POLR3A alone." (PMID 35040440, 2022).
tumor (5 papers, 2019 to 2025). "Whereas POLR3A and POLR3GL were expressed at comparable levels, POLR3G expression was on average 3.7-fold higher in tumours relative to adjacent prostate samples from the same individuals." (PMID 30820548, 2019).
infection (4 papers, 2019 to 2025). The state of being infected such as from the introduction of a foreign agent such as serum, vaccine, antigenic substance or organism. "Polr3A differential binding analysis using DiffBind confirmed that infection-associated increases in Polr3A occupancy at Pol III genes primarily occurred on type II promoters, this included B2 SINE and tRNA genes." (PMID 40768347, 2025). "We performed Polr3A ChIP-qPCR and found that increased pre-tRNA abundance was associated with higher levels of Polr3A occupancy during infection." (PMID 33323507, 2020). "CPSF30 occupancy and its correlation with Polr3A binding was still detectable, but at reduced levels when averaged across all Polr3A occupied B2 SINEs expressed during infection (n = 3,434, RPKM≥5)." (PMID 40768347, 2025). "While we did not detect CPSF30 at genes with type I (5S rRNA) and type III (U6 RNA, 7SK RNA, and Y RNA) promoters, we did detect CPSF30 at Polr3A-occupied tRNA genes (n = 295) during infection." (PMID 40768347, 2025). "Additionally, our prior B2 SINE-specific sequencing (SINE-seq) data identified infection-induced increases in B2 SINE ncRNAs from more than twice the number of loci than those with increased Polr3A occupancy detected here." (PMID 40768347, 2025). "These variants were found in inflammasome genes (NLRP1/3 and CASP1), genes mediating inflammasome inactivation via auto- and mitophagy (RIPK2 and MEFV), and genes involved in the response to infection with DNA viruses (POLR3A, DHX58, and IFIH1) and type-1 interferons (TYK2 and PTPRC)." (PMID 37626706, 2023). "These variants were found in inflammasome genes (NLRP1/3, CASP1), genes mediating inflammasome inactivation via auto and mitophagy (RIPK2, MEFV), and genes involved in response to infection with DNA viruses (POLR3A, DHX58, IFIH1) and to type-1 interferons (TYK2, PTPRC)." (PMID 31235738, 2019). "Furthermore, there was a stronger correlation between Polr3A occupancy levels and CPSF30 occupancy at tRNA genes compared to B2 SINEs during infection." (PMID 40768347, 2025). "Nearly half of the Polr3A occupied B2 SINE genes, and the majority of occupied tRNA genes, had modest to no induction of Polr3A occupancy upon MHV68 infection." (PMID 40768347, 2025).
movement disorder (2 papers, 2020 to 2022). Neurological conditions resulting in abnormal voluntary or involuntary movement, which may impact the speed, fluency, quality and ease of movement. "In 2020, reports of mutations in POLR3A gene with movement disorder and striatal involvement were published which matched our patient." (PMID 36397839, 2022).
neurodevelopmental disorder (1 paper, 2020). A behavioral and cognitive disorder with onset during the developmental period that involves impaired or aberrant development of intellectual, motor, or social functions. "The phenotype of our patient expands the clinical presentation of POLR3A-related mutations and suggests a new classification that we propose designating as Neurodevelopmental Disorder with Regression, Abnormal Movements, and Increased Lactate." (PMID 33134517, 2020).
neuromuscular disease (1 paper, 2024). "In addition, they clarified that two patients had non-neuromuscular diseases, related to NSUN2 and POLR3A genes, respectively." (PMID 37989827, 2024).
POLR3A also shares sentences with these, for which no sentence is quoted: cerebellar ataxia (3 papers); Hypodontia (3); neurodegenerative disease (3); autoimmune disease (2); glioma (2); Intellectual disability (2); lipodystrophy (2); Onset (2); Parkinsonism (2); pneumonitis (2); Attention Deficit Disorder with Hyperactivity (1); Autoimmunity (1); bacterial infection (1); Childhood onset (1); colorectal cancer (1); COVID-19 (1); developmental delay (1); epilepsy (1); Friedreich ataxia (1); generalized dystonia (1); head and neck cancer (1); hypoaldosteronism (1); immunodeficiencies (1); intrauterine growth restriction (1); leukaemia (1); lipoma (1); lymph node metastasis (1); McArdle disease (1); melanoma (1); metabolic acidosis (1).
A further 19 diseases each share a sentence with POLR3A in 1 paper.